MIR338 (microRNA 338)
Synonyms: hsa-mir-338; MIRN338; mir-338
Gene: MicroRNA gene on chromosome 17 (81,125,883 to 81,125,949, reverse strand). Ensembl gene ENSG00000283604.
Gene Ontology:
Biological process: miRNA-mediated post-transcriptional gene silencing
Cellular component: RISC complex
Diseases named in the same sentence as MIR338 in open-access papers:
MIR338 is named in the same sentence as 4 diseases in open-access papers, as found by Europe PMC text mining. Sharing a sentence is not in itself a finding about the gene and the disease.
MIR338 shares sentences with these, for which no sentence is quoted: esophageal cancer (1 paper); neuroblastoma (1); prostate (1); prostate carcinoma (1).